EGFR (epidermal growth factor receptor)
Diseases named in the same sentence as EGFR in open-access papers (continued):
Sharing a sentence is not in itself a finding about the gene and the disease.
cancer (continued). "HER family pathway activation (p-erbB2, p-EGFR, p-HER3) was common in the primary and MBC samples, with downstream activation of p-mTOR and p-STAT3 seen in several patients’ cancers." (PMID 25871911, 2015). "An earlier report has demonstrated that when HER2, EGFR and HER4 were inhibited using tyrosine kinase (TK) inhibitors, HER3 was upregulated, and this appeared to facilitate cancer cell survival and proliferation." (PMID 26035354, 2015). "Many client proteins of Hsp90, such as HER2, c-Met, EGFR, BCR-ABL, AKT and RAF1, et.al, are believed to play essential roles in cell survival, invasion, angiogenesis and other characteristic properties of cancer cells." (PMID 26097875, 2015). "Genetic silencing through transfection with siRNA of EGFR or ICAM-1 and pretreatment with inhibitors of EGFR, PI3K, Akt, NF-κB and IKK abrogated the AREG-enhanced ICAM-1 expression and cancer cell migration." (PMID 26503469, 2015). "Despite reduced phosphorylation of EGFR and EGFRvIII with TKI treatment downstream signaling pathways remain activated likely due to crosstalk and feedback of intracellular signaling in cancer cells." (PMID 25658924, 2015). "In this cancer-promoting process, IL-1β and CXCL1-CXCR2 have crucial regulating roles in integrating inflammation stimuli and an EGFR signaling cascade." (PMID 26462152, 2015). "In vitro and in vivo data showed that combinatorial inhibition of the EGFR and FGFR signaling pathways in various human cancers results in better outcomes as compared to the single regimens alone." (PMID 26581390, 2015). "This is the case of AEE788, an oral inhibitor with potent activity against multiple tyrosine kinases including EGFR, and VEGFR, which has been shown to exert antitumoral effects in various human cancer models." (PMID 26107817, 2015). "Dioscin can down regulate EGFR and EGF to inhibit cancer, and also has anti-inflammation activity by regulating JNK signaling pathway." (PMID 25879470, 2015). "Gefitinib (Iressa, ZD-1839) is a small molecule tyrosine kinase inhibitor (TKI) targeting the epidermal growth factor receptor (EGFR) signal transduction pathway that is involved in the survival and proliferation of cancer cells." (PMID 26542452, 2015). "In view of the prominent role in cancer cell biology and alteration in substantial numbers of ESCC, defining EGFR molecular characteristics relevant to patient prognosis is of great importance." (PMID 25953424, 2015). "Epidermal growth factor receptor (EGFR, also ErbB-1 or HER1) is an important drug target and prognostic indicator in many cancers." (PMID 25622307, 2015). "Pan-HER, a mixture of three synergistic pairs of antibodies against EGFR, HER2 and HER3, was recently developed and demonstrated to be superior to single receptor targeting in preclinical cancer models." (PMID 26460961, 2015). "We determined the cell-surface density of EGFR and c-MET in a panel of cancer cell lines grown under uniform conditions using flow cytometry." (PMID 26260789, 2015). "Recently, we identified that KITENIN/ErbB4-Dvl2-c-Jun axis is an unconventional EGFR-independent downstream signal of EGF and mediates the invasiveness and tumorigenesis of cancer cells." (PMID 26371759, 2015). "EGFR is a member of the RTK family and it is one of the important cancer-related signaling regulators." (PMID 25970784, 2015). "Recent evidence has also highlighted the additional roles for the MET in cancer via crosstalk with other receptors and cell surface proteins, such as TGFB1 and EGFR, and these interactions contribute to oncogenesis and drug resistance." (PMID 26267324, 2015). "More notably, strategies that dually target EGFR and IGF-1R showed better antitumor efficacy than those targeting individual receptors in cancer therapies." (PMID 25993617, 2015).
cancer (continued). "However, repeat biopsy studies have consistently suggested that the SCLC transformed cancers represent an evolution from the initial adenocarcinomas rather than a second coincident cancer, because the activating driver EGFR mutations are identical to the original adenocarcinomas in all cases." (PMID 25758528, 2015). "Western blot analysis showed that the levels of phosphorylated Src, epidermal growth factor receptor (EGFR), AKT, mTOR, and p70S6K were higher in cix-treated resistant cancer cells than cix-sensitive cells." (PMID 25699021, 2015). "Epidermal growth factor receptor (EGFR) is the earliest known RTK family protein, and is overexpressed in a wide range of cancers, playing important roles in cell growth and survival." (PMID 25738771, 2015). "In view of the prominent role in cancer cell biology and (over-)expression in substantial numbers of ESCC, EGFR represents valuable therapeutic target." (PMID 25953424, 2015). "We focused on tyrosine kinase receptors such as EGFR, RET and c-Met genes because molecularly targeted therapies aimed at inhibiting their activities have been developed recently for several types of cancer." (PMID 25405368, 2015). "Our results suggest that human cancer patients with relatively high levels of EGFR, ErbB3, and HRG are the potential patient population of the anti-EGFR/ErbB3 DVD-Ig protein treatment." (PMID 25997020, 2015). "Those segments contain well-known oncogenes, including EGFR, SOX2, and ERBB2, which are registered in the Cancer Gene Census database as amplified genes in several types of cancer." (PMID 26465158, 2015). "EGFR plays a critical role in regulating cancer cell growth and survival, representing an attractive therapeutic target in NSCLC and compounds serve as EGFR-TKIs are attracting even more and more attention." (PMID 25730907, 2015). "Moreover, as a hypothesis-generating aim, we explored the correlation between p16Ink4A status and Ki67 as well as the most common molecular aberrations in well-known targetable cancer genes, such as epidermal growth factor receptor (EGFR) and anaplastic lymphoma kinase (ALK)." (PMID 26674347, 2015). "The simultaneous inhibition of EGFR and the FAK pathway increases the apoptotic response of cancer cells." (PMID 25997441, 2015). "Among the HER family members, EGFR and HER2 have been very actively pursued as therapeutic targets in cancer." (PMID 26571416, 2015). "EGCG treatment alters the lipid rafts of cancer cells and inhibits binding of the ligand epidermal growth factor (EGF) to the EGF receptor (EGFR), which is an RTK as well, and the subsequent receptor dimerization." (PMID 25789501, 2015). "Cross-cancer alteration analysis for Abl-1, EGFR, Fyn, LCK, Src, ACK1 (TNK2) tyrosine kinases reveal that these genes are frequently altered in cancers, e.g. EGFR and TNK2 are recurrently amplified and mutually exclusive in a majority of the cancer cases." (PMID 26546517, 2015). "HER2, EGFR, FGFR2 and FGFR3 missense substitutions were observed in 10(3.5%), 1(0.4%), 5(1.8%) and 2(0.7%) of the cancers, respectively." (PMID 25669975, 2015). "FAM83B has been reported as an important intermediary in EGFR/RAS signaling, and is highly expressed at the mRNA level in several cancers, including breast, cervix, bladder, lung, testis thyroid, and ovary cancer." (PMID 25586059, 2015). "Lysosome inhibitor NH4Cl reversed WJ-induced EGFR degradation as well as growth inhibition, indicating that EGFR plays an important role in HDAC inhibition-induced anti-cancer effect." (PMID 25980579, 2015). "As, H2170 cells have upregulated and constitutively activated p-EGFR, this suggests that EGFR and Wnt pathways may converge at β-catenin, and thus, cooperatively enhance tumorigenesis in H2170-ER and H2170-SR cells, which has also been suggested by other investigators in other cancers." (PMID 26301867, 2015).
cancer (continued). "Taking into consideration enhanced EGFR expression and a high physiological level of EGF, this confirms interplay between cancer cells and epithelial lung cells in determining cancer development." (PMID 25598217, 2015). "Mechanistic studies show that CUDC-101 integrates HDAC and EGFR/HER2 pathway inhibition, blocks and inhibits MET- and AXL-mediated signaling, and reduces cancer cell migration." (PMID 25940539, 2015). "The bidirectional interplay of EGFR and ANO1 highlights the importance of the functional complex formed between both proteins in regulating proliferation of cancer cells." (PMID 25823819, 2015). "Interaction between the epidermal growth factor receptor (EGFR) and the insulin-like growth factor receptor (IGF-1R) has been well established in many cancer types." (PMID 25355701, 2015). "EGFR, an essential RTK, playing an vital role in cell differentiation, proliferation, and survival in a number of human cancers, also contribute to both de novo and acquired trastuzumab resistance." (PMID 26474285, 2015). "Since the anti-cancer mechanism of TMS is different from that of current EGFR TKIs, by not only directly targeting EGFR but exerting multi-targeting effect on EGFR as well as crosstalk pathways." (PMID 26542098, 2015). "Epidermal growth factor receptor (EGFR) and its ligand, epidermal growth factor (EGF), are overexpressed in many malignancies, including cancers of the head and neck, breast, kidney, lung, colon, ovary, prostate, brain and spine, pancreas, and bladder." (PMID 25723471, 2015). "Overexpression of the human epidermal growth factor receptor (HER) family and their ligands plays an important role in many cancers." (PMID 26460961, 2015). "A recent study reported that BPD-mediated PDT initiates nuclear signaling of EGFR and STAT3 which results in decreased cancer cell cytotoxicity following PDT." (PMID 25918252, 2015). "In cancer therapy, drugs acting on the HER2 (erb-b2 receptor tyrosine kinase 2) and EGFR (epidermal growth factor receptor) pathways have shown this type of drug evasion effects." (PMID 26047322, 2015). "In fact, silencing cancer cell EGFR expression or immunodepletion of EGF from macrophage CM, led to inhibition of motility, and abrogation of cancer cell invasion." (PMID 26043921, 2015). "Pancreata of mice receiving combination treatment showed significantly fewer Dclk1-positive cancer stem-like cells, inhibition of COX-2, 5-LOX, PCNA, EGFR and β-catenin expression (p < 0.05–0.0002), increased p21 expression." (PMID 26429877, 2015). "The Kirsten rat sarcoma viral oncogene homolog (KRAS) protein is an important signaling mediator in the epidermal growth factor receptor (EGFR) pathway, which regulates cell growth and is commonly targeted in cancer therapy." (PMID 25823645, 2015). "EGFR and EGF-EGFR signaling has been documented to be of critical relevance in iUC, and in other human cancers as well." (PMID 26352142, 2015). "Monoclonal antibodies are being successfully used in immunotherapy of diseases such as cancer where they target antigens such as HER2 using trastuzumab (Herceptin), EGFR with panitumumab (Vectibix) and VEGF-A with bevacizumab (Avastin)." (PMID 26611870, 2015). "For both EGFR and ERK, activity changes were inconsistent between human cancer cell lines and mouse tissues." (PMID 25896712, 2015). "Recent studies showed that honokiol can target EGFR, AMPK, Notch signalings in various cancer cells; further supporting the idea that honokiol can regulate multiple pathways to inhibit cancer cells." (PMID 26484567, 2015). "Besides, using genomic DNA of MKN-28, Gene Tech (Shanghai) company (Shanghai, China) performed EGFR mutation assays in exons 18, 19, 20, and 21, which are the hotspots of EGFR mutations in the current cancer research, and no mutations in these regions were identified through pyrosequencing." (PMID 25590805, 2015).
cancer (continued). "In this study, we demonstrated that Amiodarone caused the ectopic expression of versican V2, conserved as zebrafish ortholog s-vcanb, and cancer growth/metastasis inhibition through EMT modulation and suppressing EGFR signaling." (PMID 26515726, 2015). "Activation of EGFR would stimulate its downstream kinases including PI3K, Akt, and mTOR25, and thus enhance and prolong cancer cells growth and survival." (PMID 26542098, 2015). "Therefore, we propose that blockage of constitutive dimerization of C-terminal exonic deletion mutants with cetuximab may be an effective novel therapeutic strategy to treat a subset of cancer patients, along with patients harboring dimerization-dependent L858R and G724S oncogenic EGFR mutants." (PMID 25826094, 2015). "Current evidences showed that NF-κB is a major transcriptional factor mediating LMP-1 induced changes of expressions of cancer-related genes including survivin, MMP-9, and EGFR in NPC." (PMID 25861643, 2015). "STAT3 is activated in EGFR wild-type NSCLC and correlates with cancer progression, including cell survival, migration and invasion." (PMID 25955608, 2015). "The combination of EGFR TKI and radiation has enhanced effects for inhibition of proliferative and antiapopotic signaling pathways downstream of EGFR in cancer cell lines." (PMID 26048754, 2015). "Another study reported that ERK1/2 and EGFR-PI3K-Akt pathways seem to be involved in cellular survival after PDT and EGFR inhibitors and PDT act synergistically to reduce malignant tumors effectively." (PMID 25918252, 2015). "The epidermal growth factor receptor (EGFR), a receptor tyrosine kinase (RTK), is a well characterized target for anti-cancer therapies for a variety of cancer types." (PMID 26209091, 2015). "We previously reported that cetuximab, an EGFR-blocking antibody, inhibits cancer metabolism via downregulation of HIF-1α and reverses the Warburg effect in cancer cells." (PMID 25871473, 2015). "Epidermal Growth Factor Receptor (EGFR) and folate receptors are two well-known overexpressed proteins in cancer cells used for designing antibody-gold nanoconjugates for active targeting." (PMID 28347100, 2015). "Therapeutic targeting of EGF/EGFR and VEGF/VEGFR signaling is a major approach of anti-cancer therapy." (PMID 24945674, 2014). "The EGFR is commonly expressed in NPC cells and is one of the identified molecular targets for cancer treatment." (PMID 25289091, 2014). "Epidermal growth factor receptor (EGFR or HER-1) and its analog c-erbB-2 (HER-2) are protein tyrosine kinases correlated with prognosis and response to therapy in a variety of human cancers." (PMID 24454858, 2014). "Our and other laboratories have reported that a specific inhibitor for EGFR efficiently blocked EGF-induced activation of MMP9 and reduced cancer invasiveness." (PMID 25380967, 2014). "As a potent oncogene, SRC regulates the proliferation and motility of cancer cells by affecting the FAK, EGFR, and Ras/ERK signaling pathways." (PMID 25140799, 2014). "The receptor tyrosine kinases (RTK) like epidermal growth factor receptor (EGFR), Ras/Raf/MEK/ERK, and PI3K/AKT pathways are all involved in cancer development, progression, and metastasis." (PMID 25122124, 2014). "Studies showed EGFR is overexpressed in up to 80% of NSCLC and become a promising target for anti-cancer therapy." (PMID 24884778, 2014). "Induced by oncogenes, such as K-ras and the epidermal growth factor receptor (EGFR), TF is overexpressed in many cancers." (PMID 25407022, 2014). "ERBB3 limits the impact of exclusively targeting ERBB1/EGFR or ERBB2/HER2 and provides a route for acquired resistance to anti-cancer drugs that inhibit ErbBs." (PMID 25248370, 2014). "The erbB receptors, including the epidermal growth factor receptor (EGFR), erbB2 (also known as HER2/neu), erbB3 (or HER3), and erbB4 (or HER4), are often aberrantly activated in a wide variety of human cancers." (PMID 24886126, 2014).
cancer (continued). "The molecular pathway of gene ANXA1 in the modulation of carcinogenesis is related to its action as a substrate to the epidermal growth factor receptor (EGFR) and protein kinase C (PKC), which implies its involvement in signal transduction pathways to cancer." (PMID 24719523, 2014). "Gefitinib is a synthetic anilinoquinazoline and orally active selective EGFR-TKI that blocks the signal transduction pathway involved in the proliferation and survival of cancer cells." (PMID 24874286, 2014). "In agreement with previous study results, the present data suggest that HER3 is a common key regulator of the proliferation of EGFR-and HER2-dependent cancer cells." (PMID 25594012, 2014). "In the present study, basal-like cancer was defined as ER−, PgR−, HER2−, CK 5/6+ and/or EGFR+ tumors using immunohistochemical surrogate markers." (PMID 24932232, 2014). "Second, our pipeline was able to recapitulate most known translocation events in cancer (ALK, BRAF, EGFR, FGFR1, 2 and 3, NTRK1, 2 and 3, PDGFRA, PRKCA, RAF1, RET, ROS1)." (PMID 25204415, 2014). "EGFR and ERK are also emerging as major effectors of eHsp90-mediated cell motility in wounding and cancer." (PMID 24805867, 2014). "It has been reported that EGFR inhibition efficiently blocked EGF-induced activation of MMP9 and cancer invasiveness." (PMID 25380967, 2014). "CIC is thought to act as a transcriptional repressor, regulating target gene expression of activated epidermal growth factor receptor (EGFR), Ras/Raf, and MAPK cancer pathways." (PMID 24716189, 2014). "EGFR/MAPK and Rb/E2F pathways intersect in the regulation of proliferation and cell death and are frequently disrupted in cancer." (PMID 25058496, 2014). "To confirm the efficacy of kinase inhibitors, we focused on three kinases for which inhibitors are currently in clinical use or development for cancer treatment: AKT, ABL and Epidermal growth factor receptor (EGFR)." (PMID 24586159, 2014). "ERBB2 encoding the protein HER2 (human epidermal growth factor receptor 2) is a member of the epidermal growth factor receptor (EGFR) family, and it has been shown to play an important role in the pathogenesis and progression of many different types of cancer." (PMID 25106096, 2014). "In both the primary cancers and the metastases, Claudin-4 was most frequently expressed, followed by GLUT-1, CAIX, EGFR and IGF1R." (PMID 25417118, 2014). "Recently, EGFR- tyrosine kinase inhibitors (TKIs) and ALK inhibitors have been used widely in clinical settings as standard cancer therapies, and PTK-targeted therapies have demonstrated clinical success in the treatment of NSCLC." (PMID 24894011, 2014). "We further reported an HER2 antibody which blocks HER2/HER3 dimerization can induce ligand independent HER3 dimerization with EGFR in both low and high HER2 expressing cancer cells." (PMID 25400118, 2014). "Molecules such as Her2, EGFR, VEGFR, ALK, AKT, p52, cyclin D1, Met, Cdk4, HIF-1α or MMP2 which play important roles as oncogenes and are involved in essential pathways of cancer are described to be client proteins of HSP90." (PMID 24978439, 2014). "The epidermal growth factor receptor (EGFR) has been observed to be upregulated in a number of tumors and is considered a target for cancer therapy." (PMID 25120710, 2014). "In both the primary cancers and the metastases, Claudin-4 was most frequently expressed, followed by GLUT-1, CAIX and EGFR." (PMID 25417118, 2014). "Intense efforts have been made to inhibit the activities of the ERBB1/EGFR and ERBB2/HER2 receptors in cancer patients by designing antibodies against the ligand binding domains or small molecules against the tyrosine kinase domains." (PMID 25248370, 2014). "Epidermal growth factor receptor (EGFR) is a family member of EGF-related tyrosine kinase receptors, and expressed at high levels in many cancer cell types, including NSCLC." (PMID 24884778, 2014).